ATR (ATR checkpoint kinase)
Diseases named in the same sentence as ATR in open-access papers (continued):
Sharing a sentence is not in itself a finding about the gene and the disease.
cancer (continued). "In cancer cells, ATR activity is crucial to tolerate the intrinsically high level of DNA lesions and obstacles that block replication fork progression." (PMID 41190242, 2025). "ATR is altered in 2.88% of multiple cancer types reported in an AACR Project GENIE Consortium study." (PMID 39941729, 2025). "Simultaneously, developing radiosensitizers tailored to genetic vulnerabilities (e.g., PARP inhibitors for SMAD4- or BRCA-mutant tumors, ATR inhibitors for ATM-overexpressing cancers) will expand therapeutic options." (PMID 40725389, 2025). "ATR inhibitors (ATRi) are in clinical development for treating various cancers, including those with high replication stress, such as is elicited by ARID1A deficiency, but the cellular mechanisms that determine ATRi efficacy in such backgrounds are unclear." (PMID 39779698, 2025). "Numerous studies have demonstrated the effectiveness of ATR inhibitors in inducing synthetic lethality in cancer cells." (PMID 41392982, 2025). "In 2023, Nanjing Damei Biopharmaceutical developed ATR inhibitors particularly effective against cancers with impaired DNA repair mechanisms, including those with BRCA1/2 mutations, PTEN loss, or ATM deficiency." (PMID 40256842, 2025). "Specifically, our findings indicate that in cancers where high AEP expression levels are associated with poor prognosis, the opposite is observed for ATR." (PMID 40012043, 2025). "Cancer cells have higher levels of replication stress and greater dependence on ATR, making ATRi a promising strategy for sensitizing cancer cells to DNA repair and replication-targeted therapies." (PMID 40356722, 2025). "In 2025, Jazz Pharmaceuticals patented an ATR-PARP inhibitor combination designed to overcome PARP resistance by disrupting DNA repair in cancer cells." (PMID 40256842, 2025). "ATR depletion thus impaired the 3D invasion and lung homing of cancer cells, revealing a potentially critical role in metastasis." (PMID 39866838, 2025). "Here we found that inducing replication stress in parental cancer cells or shp16 cells with high endogenous DNA damage increased cholesterol levels in an ATR-dependent manner (G and EV3B–D)." (PMID 40514450, 2025). "PARP5 deletion inhibits HNSCC tumor growth by activating ATR, depleting cancer stem cells, and impairing NHEJ repair." (PMID 40904702, 2025). "The rationale for this combination stems from emerging evidence that inhibition of the DDR, particularly through ATR blockade, not only enhances cancer cell death but also amplifies anti-tumor immune responses." (PMID 40869030, 2025). "Here, we demonstrated that targeting the ATR/CHK1 axis triggers cancer cell-intrinsic immunogenicity by the STING-mediated DNA-sensing pathway to enhance the therapeutic efficacy of radiotherapy and ICBs in ARID1A-deficient tumors." (PMID 40750787, 2025). "There is recent interest in MCC and other cancers for combining ATR inhibitors with immunotherapy to increase responses." (PMID 40491496, 2025). "A similar therapeutic approach can be envisioned targeting Claspin, since, due to RS, the ATR–Claspin–Chk1 pathway is often over-activated in cancer cells." (PMID 41009395, 2025). "ATR inhibitors are being developed for treating cancers, but mechanisms that determine their efficacy are unclear." (PMID 39779698, 2025). "Together, these data indicate that ATR regulates LSS to increase cholesterol levels in p16 knockdown cancer cells." (PMID 40514450, 2025). "Cancer cells eventually adapt to oncogene-induced RS, however, by overexpressing downstream components of the ATR pathway, such as Claspin, Timeless, and CHK1, which correlates with poor prognosis in breast, lung, and colon carcinomas." (PMID 39887032, 2025). "For example, ATR has emerged as a key target for overcoming resistance to PARP inhibitors in cancer, particularly ovarian cancer." (PMID 40739089, 2025).
cancer (continued). "This suggests a synthetic lethal approach: target ATR or other genome stability pathways in cancers with high R-loop load to induce catastrophic failure of repair." (PMID 40332372, 2025). "Although it is an essential kinase, ATR has emerged over the years as a promising anti-cancer drug target." (PMID 38880245, 2024). "DNA damage is first recognized by molecular “sensors”, most notably those in the ATR/Chk1- and ATM/Chk2-mediated signalling pathways, which are hyperactivated in various cancers and associated with chemoresistance and poor prognosis." (PMID 38685067, 2024). "Targeting DNA repair pathways alongside HER2 inhibition has also shown potential; combining PARP and ATR inhibitors with HER2-targeted ADCs effectively increases antitumor activity in resistant HER2-positive cancers." (PMID 39684551, 2024). "ATR kinase maintains accurate DNA replication by regulating the DNA replication initiation and the process of replication forks, supporting that ATR is an important target for cancer therapy." (PMID 38763973, 2024). "It was demonstrated that PD-L1 expression in cancer cells is upregulated in response to DSBs and requires ATR/CHK1 kinases." (PMID 38279263, 2024). "ATM and ATR are induced in cancer cells exposed to chemotherapy and blocking them is proposed as an attractive strategy to overcome resistance in cancer patients." (PMID 38366255, 2024). "In HER2+ cancers, there is an ongoing phase I/IB clinical trial of the combination of T-DXd and an ATR inhibitor in patients with advanced solid tumors expressing the HER2 protein or gene (DASH trial, ClinicalTrials.gov identifier: NCT04704661)." (PMID 39164784, 2024). "For instance, treatment of cancer cells with the ATR inhibitor AZD6738, in combination with protons of two LET values (1 and 7 keV/μm) or X-rays, revealed equal radiosensitization for all radiation types." (PMID 38920686, 2024). "As such, ever since Ataxia Telangiectasia Mutated and Rad3-related protein (ATR) was discovered to be a crucial component in the DDR pathway, developing strategies to target ATR have gained significant popularity as a cancer therapy." (PMID 39456630, 2024). "In conclusion, our study presents evidence that induction of DDR is a hallmark of any cancer cells experiencing an acidic milieu and that ATM and ATR inhibitors can directly take advantage of this context." (PMID 38366255, 2024). "To further support the activation of ATM and ATR pathways under acidosis, we examined them in cancer cells exposed to genotoxic 5-fluorouracil (5-FU)." (PMID 38366255, 2024). "Inhibiting ATR is of particular interest because of its central role in activating G2 cycle arrest, which cancer cells rely on heavily, as the G1 checkpoint is often defective." (PMID 39235982, 2024). "Although the ATM gene has a significant mutation rate in many human cancers, including colorectal, prostate, lung, and breast, it remains understudied compared with other DDR-involved molecules such as PARP and ATR." (PMID 39033176, 2024). "The DDR provides genomic instability, which is an enabling characteristic of cancer, and cancer cells are particularly reliant on the ATR–Chk1 pathway." (PMID 38673980, 2024). "ATR inhibitors are particularly effective in cancers with high levels of replication stress or when used in combination with agents that induce replication stress." (PMID 39372203, 2024). "Because cancer cells depend heavily on the DNA damage checkpoint for their unchecked proliferation and propagation, ATR has gained enormous popularity as a cancer therapy target in recent decades." (PMID 39456630, 2024).
cancer (continued). "It has been shown that purified His-tagged recombinant human APE1 protein can activate the ATR-Chk1 DDR pathway in nuclear extract of cultured human cancer cells." (PMID 39112456, 2024). "Our results illustrate a novel potential approach for individualized cancer therapy using specific ATR/CHK1 inhibitors or POLA1 inhibitors for the individualized treatment of ATR- or POLA1-deficient tumors, respectively." (PMID 39128273, 2024). "Both ATM and ATR DDR pathways are being targeted in clinical trials for diseases such as cancer, which highlights the significance of basic mechanistic studies on how ATM and ATR are activated to maintain genome stability." (PMID 39112456, 2024). "Drugs targeting ATM and ATR preferentially inhibit growth of acid-exposed cancer cells and sensitize them to chemotherapy." (PMID 38366255, 2024). "For example, ATM depletion makes cancer cells more sensitive to ATR inhibitors or DNA damage, which ensures high levels of IFN expression dependent on the cGAS–STING signaling pathway." (PMID 38630271, 2024). "Here the authors report the anti-tumor activity and the immunomodulatory changes, dependent on up-regulation of type I interferon pathway, following intermittent ATR inhibition in preclinical cancer models." (PMID 38402224, 2024). "The ATR inhibitor ceralasertib has shown clinical activity in combination with immune-checkpoint inhibitors in several cancer types." (PMID 38402224, 2024). "Several groups and pharmaceutical companies have focused on the identification of ATR inhibitors for cancer treatment, and four molecules targeting ATR are currently in clinical studies, namely, VX-970, VX-803, BAY1895344 and AZD6738." (PMID 39206868, 2024). "ATR/CHK1 pathway inhibitors have been studied as a therapeutic strategy to target cancers with high levels of RS, e.g., platinum-resistant HGSOC7." (PMID 38555285, 2024). "Conversely, we demonstrated that siRNA-mediated POLA1 depletion sensitized several cancer cell lines towards chemical inhibition of ATR and its main effector kinase CHK1." (PMID 39128273, 2024). "With these newly identified functions, it is important to reevaluate the clinical strategies and implications of ATR inhibitors as a cancer therapy." (PMID 39456630, 2024). "Collectively, this work reveals the RPAi mechanism of action to inhibit ATR signaling that can be regulated by RPA PTMs and offers insight into the anti-cancer activity of ATR pathway targeted cancer therapeutics." (PMID 39108493, 2024). "Gartisertib (M4344) is an orally administered ATR inhibitor that has shown highly potent antitumour activity in several cancer cell lines, patient-derived tumour organoids and mouse xenograft models." (PMID 38287179, 2024). "Through this summary, we also address the need for re-assessing clinical strategies targeting ATR as a cancer therapy based on these newly discovered roles for ATR." (PMID 39456630, 2024). "MYC-driven cancer cells, in which RS is limited and tumor growth is supported by ATR/Chk1 activation, exhibit higher sensitivity to ATR and Chk1 inhibitors." (PMID 39456601, 2024). "Taken together, the use of RPA inhibitors as RPA- and ATR-inhibiting, anti-cancer agents is multifaceted and will have significant clinical ramifications as RPA serves numerous functions in DNA metabolism." (PMID 39108493, 2024). "Cancer cells rely on the ATR–Chk1 pathway for the regulation of replication stress and the DNA damage response (DDR)." (PMID 38673980, 2024). "Previous in vitro studies have presented the potential activity of several ATR inhibitors in various cancer cell lines." (PMID 38827321, 2024). "VE 822, an ATR inhibitor also known as Berzosertib, significantly enhances radiosensitivity in several cancers such as esophageal cancer, colorectal cancer and melanoma and is currently being evaluated in phase I and II studies." (PMID 39411143, 2024).
cancer (continued). "As such, ATR is an important component of the cellular response to radiation, particularly in cancer cells, which show altered DNA damage response and aberrant cell cycle checkpoints." (PMID 39235982, 2024). "At the expression level, a positive correlation between HDAC8 and CHK1 or ATR was also found in pan-cancer datasets, suggesting coregulation between these genes in many tumor types." (PMID 39436709, 2024). "Preclinical data suggest a synthetic lethal interaction between targeted ATR therapy and ARID1A deletion mutations in ovarian clear cell carcinoma and other cancer cell lines." (PMID 39697230, 2024). "We previously reported that the W119R mutation within human APE1 impaired its ability to directly activate ATR DDR in cancer cells." (PMID 39112456, 2024). "In this review, the premise and promise of ATR as a target of cancer therapy is based on the idea of synthetic lethality." (PMID 39456630, 2024). "At the same time, kinome analysis suggested an activation of CHK1/ATR axis in cancer cells shortly after the drug exposure." (PMID 38783016, 2024). "We find that regardless of the cell replication error status, both ATM and ATR inhibitors exert preferential growth inhibitory effects on acid-exposed cancer cells." (PMID 38366255, 2024). "Overall, ATR inhibitor combinatorial therapy with other DNA damaging agents or PARP inhibitors have shown great promise with high degrees of cytotoxicity in cancer cells." (PMID 39456630, 2024). "This notion is further supported by studies showing the synergistic anti-cancer effects of the combination of ATR inhibition and DNA damage–inducing chemotherapy." (PMID 38195460, 2024). "While numerous studies have already examined the effectiveness of ATM and ATR inhibition alone or in combination with RT for different cancer types, there remains a notable gap in directly comparing their impact on the immunogenicity of HNSCC cells." (PMID 39411143, 2024). "Long-term treatment with ATR inhibitors(ATRi) can render HR-proficient cancer cells sensitive to PARPi." (PMID 39156700, 2024). "Currently, targeting ATR is also considered a potent strategy to overcome cancer resistance, and several ATR inhibitors are in clinical trials." (PMID 37775817, 2023). "ATM and ATR are two critical factors to regulate DNA damage response (DDR), and their mutations were frequently observed in different types of cancer, including non-small cell lung cancer (NSCLC)." (PMID 38041093, 2023). "We propose using cis-ATR as a novel, potential cancer treatment target by taking advantage of the natural balance that exists in normal human cells between cis-ATR and trans-ATR isoforms." (PMID 37511442, 2023). "ATR (ataxia telangiectasia mutated and Rad3-related) kinase, a major regulator of DDR, has shown significant therapeutic potential in cancer treatment." (PMID 37511442, 2023). "Inhibiting ATR activity elevates the sensitivity of cancer cells to genotoxic agents and/or induces apoptosis." (PMID 36902170, 2023). "Since ATM and ATR are the first molecules activated after DNA damage, their dual inhibition with Top2 inhibitors made them a potential combination therapy for cancer proliferation arrest and apoptosis." (PMID 36678591, 2023). "In this context, cancer cells often suffer from oncogenic replication stresses that enhance their senstivity to ATR inhibition." (PMID 37336885, 2023). "The co-treatment of cells with both PARP and ATR inhibitors has now been explored in further detail and entered clinical trials for a number of cancers, including CRPC." (PMID 38201511, 2023). "It was reported that combined inactivation of CTPS1 and ATR is synthetic lethal to cancer cells, further highlighting the potential link between CTPS family and DDR signaling." (PMID 36635772, 2023). "Regarding the mutation hotspots and mutation types in cancer, most of the truncating mutations of ATM, ATR, CHEK1, and CHEK2 are considered to be, at least, likely pathogenic." (PMID 37373360, 2023).
cancer (continued). "Cancer immunotherapy can be improved by activating the cGAS-STING pathway, which has been linked to the inhibition of ATM, ATR, CHK1, and PARP." (PMID 36831197, 2023). "Additional investigations have revealed that the co-inhibition of POLH and ATR, a protein that is central to the replicative stress response, offers an SL approach for the treatment of a range of cancer types." (PMID 38068959, 2023). "The inhibitors of DDR have been extensively developed, including ATM, ATR, and DNA-dependent protein kinase (DNA-PK) to deal with cancer cells." (PMID 36794257, 2023). "Since most cancer cells have dysregulated G1 checkpoints, they are mostly dependent on S and G2 checkpoints activated by the ATR/CHK1 pathway." (PMID 37091174, 2023). "The goal of this study was to comprehensively analyze the synergistic relationship between the inhibitors of canonical DDR kinases (ATM, ATR, and DNA-PK) and a panel of anti-cancer drugs." (PMID 38097586, 2023). "Sensitivity of human ATM-mutated cells from various cancers to combinations of PARP inhibitors and ATR inhibitors has been observed." (PMID 36975505, 2023). "NU6027, an ATR inhibitor, can increase the sensitivity of certain types of cancer, such as breast cancer, to irradiation and other cancer therapies." (PMID 36902170, 2023). "In order to survive PARP inhibition, cancer cells rely more on ATR checkpoint to slow down cell cycle and reduce replication stress for repairing DSBs." (PMID 36650183, 2023). "As a result, using irradiation or chemotherapy to target cis-ATR as an adjuvant treatment for cancer should preferentially kill cis-ATR-dependent cancer cells while having little influence on the normal activities of nuclear trans-ATR in cells." (PMID 37511442, 2023). "To visualize these global relationships, we generated comprehensive heatmaps showing the efficacy and synergy responses of all 87 anti-cancer drugs screened in combination with six ATM/ATR/DNA-PK inhibitors across all 62 cell lines and 12 tissues." (PMID 38097586, 2023). "Pharmacologic inhibition of the EGFR, mTORC1 and ATR pathways represent therapeutic options in several cancer types." (PMID 37202753, 2023). "Inhibitors of CHK1 and ATR have promising potential for cancer therapeutics, either alone or by sensitizing cells to DNA-damaging anti-MM agents." (PMID 37627183, 2023). "For example, PARP and ATR inhibition increases genomic instability and cell death in ATM-deficient cancer cells." (PMID 36794257, 2023). "As upstream regulators of these cyclins and CDKs, ATM, ATR, CHK1, and CHK2 are among the most common cell cycle dysregulation events that promote cancer susceptibility across cancer types." (PMID 37390209, 2023). "The ATR/Chk1 signaling pathway is often upregulated in cancer and promotes tumor growth; consistently, ATR and Chk1 inhibitors kill tumor cells." (PMID 37762228, 2023). "The rationale for targeting ATR in cancer is that malignant cells are often adapted to replication stress, which requires a functional ATR/CHK1/WEE1 axis, which is particularly evident when certain DNA-damaging agents are used." (PMID 37041372, 2023). "Perturbation of the ATR-Chk1 pathway induces deleterious consequences, thus can be exploited to treat cancer in which RS levels are always augmented because of oncogene hyperactivation." (PMID 37270643, 2023). "The most commonly used ATR inhibitors in cancer clinical studies are specific inhibitors of the enzyme ATR kinase, which plays a key role in the DNA damage checkpoint function of ATR in the nucleus." (PMID 37511442, 2023). "It is widely recognized that the ATR/CHK1 signaling pathway is commonly upregulated in cancer and promotes tumor growth." (PMID 37762228, 2023). "Our study provides a potent therapeutic target of the ATR-scaRNA2 complex for overcoming cancer resistance." (PMID 37775817, 2023).